IDO1 (indoleamine 2,3-dioxygenase 1)
Diseases named in the same sentence as IDO1 in open-access papers (continued):
Sharing a sentence is not in itself a finding about the gene and the disease.
cancer (continued). "More than fifty clinical trials have been registered in ClinicalTrials.org using IDO1 inhibitors for cancer treatment (ClinicalTrials.org)." (PMID 32907554, 2020). "Our research demonstrates for the first time the use of malignant ascites as a source of biomarkers for clinical research on IDO1." (PMID 33584686, 2020). "In fact, the overexpression of IDO-1 in cancer cells helps to evade immune surveillance by suppressing the expansion of T-cells and other immune cells." (PMID 33330446, 2020). "IDO1’s metabolic function was initially thought to mediate a survival strategy to deprive bacteria and cancer cells of tryptophan." (PMID 33584695, 2020). "Tryptophan pathway regulated by the rate-limiting enzyme, indoleamine-2,3-dioxygenase (IDO-1), has evolved as a therapeutic target in immunosuppression-induced cancer autoinflammatory diseases." (PMID 32244920, 2020). "In certain cancers, IDO1 is overexpressed, and is thought to promote cancer progression in part by decreasing exogenous levels of tryptophan, which serves as an immune detection signal." (PMID 32493904, 2020). "IDO1 is expressed in tumoral cells and adaptive immune response cells, and its reactivity correlates with a shorter survival in several cancers." (PMID 32380691, 2020). "Tryptophan catabolism by the enzymes indoleamine 2,3-dioxygenase 1 and tryptophan 2,3-dioxygenase 2 (IDO/TDO) promotes immunosuppression across different cancer types." (PMID 32782249, 2020). "Indoleamine 2.3-dioxygenase-1 (IDO1) is an intracellular enzyme and overexpressed in various cancers." (PMID 32195194, 2020). "This was based on the known overexpression level of IDO1 in cancer cells and modulatory role in cancer development and malignancies." (PMID 32245062, 2020). "Unfortunately, clinical trials using IDO1 inhibitors to treat various types of cancer have been unsuccessful, potentially due to redundant functions played by IDO2 and TDO2." (PMID 31922097, 2020). "More importantly, gut-microbiota can affect the disease state of cancer by modulating IDO-1 activity (see Section “Kynurenine Pathway”) through regulating AhR activity." (PMID 33330446, 2020). "IDO1 expression has been correlated with poor prognosis, increased progression and reduced survival in several cancers." (PMID 33584686, 2020). "IDO1 expression has been related to poor prognosis in several cancers and to resistance to checkpoint immunotherapies." (PMID 33584686, 2020). "It is suggested that IDO1 takes different positions in the three phases of cancer immunoediting: elimination, equilibrium, and escape." (PMID 32153576, 2020). "TDO is expressed constitutively by the liver, but also in in certain tumors, which suggests a possible functional role in cancer immunosuppression which can be independent or complementary to that of IDO1." (PMID 32637034, 2020). "IDO1 elevation has pivotal roles in tumorigenesis and immunosuppression, resistance to chemotherapies and is correlated to shorter survival in cancer patients." (PMID 32499786, 2020). "IDO-1 is mainly responsible for tryptophan degradation and highly expressed in multiple types of human cancer, including acute myeloid leukemia." (PMID 32039024, 2019). "Our data elucidate the role of H2S in the regulation of IDO1 and provide a novel strategy to target H2S for cancer immunotherapy." (PMID 30777103, 2019). "Indoleamine 2,3 dioxygenase-1 (IDO1) is an enzyme mostly found in DC and an appealing target for cancer immunotherapy." (PMID 31060337, 2019). "IDO1 is constitutively expressed in more than half of human cancers, such as ovarian and colorectal cancer." (PMID 31324754, 2019). "IDO1 inhibition for cancer therapy has been exploredmuch earlier and will be discussed here along with TDO inhibition." (PMID 31105983, 2019). "In particular, DX-03-12 and DX-03-13 showed IDO1 inhibition with IC50s of 0.3 and 0.5 μM and low cell cytotoxicities against two cancer cell lines." (PMID 31195673, 2019).
cancer (continued). "Many cancers express high levels of TDO2 and IDO1, and high tumoural IDO1 expression is associated with poor patient outcomes." (PMID 31795096, 2019). "The findings reported herein demonstrate that the YSK12-MEND represents an effective delivery system for IDO1-silenced DC based cancer immunotherapy." (PMID 31383907, 2019). "The YSK12-MEND appears to be a potent delivery system for IDO1-silenced DC based cancer immunotherapy." (PMID 31383907, 2019). "Increased IDO1 of cancer cells directly resulted in tryptophan exhaustion in microenvironment and reduced the activation of immune cells." (PMID 31315643, 2019). "Herein, we applied the virtual screening technique in conjunction with the cell based kynurenine assay to identify TDO2-specific and dual IDO1/TDO2 inhibitors with potential for further development into drug candidates for cancer immunotherapy." (PMID 31795096, 2019). "Developments of small molecules based IDO1 inhibitors are becoming increasingly important, because of the crucial role of the IDO1 enzyme in cancer immunotherapy." (PMID 31804586, 2019). "Among those, IDO1, an enzyme that catabolizes tryptophan to kynurenine acid and thereby provides metabolic advantage to cancer cells against T cells, was found to be of utmost importance." (PMID 31514488, 2019). "Recently, multiple studies, including si-RNA, IDO1 null mice, and small-molecule inhibitors, have appeared validating IDO1 as a therapeutic target for cancer immunotherapy." (PMID 30734612, 2019). "Inflammation can induce more indoleamine 2,3-dioxygenase 1 (IDO1), which benefits cancer immune escape by producing kynurenine." (PMID 31850199, 2019). "The overexpression of IDO1 enzyme is also correlated with poor prognosis in different types of cancers, including colorectal, pancreatic, and ovarian." (PMID 31804586, 2019). "Berberine and its derivatives are shown to exhibit anti-cancer activity through cell killing by NK cells via IDO1." (PMID 31719837, 2019). "Over-expression of IDO1 corrects with poor prognosis in different types of cancers, including melanoma, pancreatic, ovarian, colorectal, and others." (PMID 30734612, 2019). "In the current study, an in silico molecular modeling study revealed the plausible binding modes of discorhabdins in two additional cancer target enzymes, topoisomerase I/II and IDO1." (PMID 31349703, 2019). "Over-expression and over-activation of immunosuppressive enzyme indoleamine 2, 3 -dioxygenase 1 (IDO1) is a key mechanism of cancer immune escape." (PMID 30777103, 2019). "The results indicate that the YSK12-MEND represents a promising system for achieving IDO1-silencing DC-based therapy against cancer." (PMID 31383907, 2019). "Although IDO1 is a very important immune checkpoint controller, preclinical studies have noted that single-agent treatment with an IDO1 inhibitor has a negligible effect on decreasing the established cancer burden." (PMID 31511064, 2019). "Human cancerous tissue expression of IDO1, IDO2and TDO2 has been studied.Many types of cancers express IDO1, whereas that of IDO2 is negligible." (PMID 31105983, 2019). "While it is still too soon to draw conclusions about the therapeutic potential of IDO1 inhibitors for HIV disease and cancer, an increasing number of IDO1 inhibitors are currently in preclinical development or under evaluation in clinical trials." (PMID 31316514, 2019). "Drugs targeting this signaling pathway and specifically IDO1 have already underwent clinical trials with the aim to revert immunosuppression induced by cancers." (PMID 31775797, 2019). "Combination therapy with an IDO-1 inhibitor plus checkpoint inhibitors in patients with several cancer types is being tested in a clinical trial." (PMID 30682105, 2019). "IDO1, a key dioxygenase in tryptophan-kynurenine metabolism, appeared in the last 10 years at the vanguard of druggable targets in cancer therapy due to its well-established role both in immune escape and inflammatory neovascularization." (PMID 31096672, 2019).
cancer (continued). "We report here on confirming the potency of the YSK12-MEND in IDO1-silenced DC-based therapy against cancer." (PMID 31383907, 2019). "Up-regulation of IDO1 promoted cell growth of MGC-803 cancer cells, but attenuated cell growth at 24 h in HGC-27 cancer cells (all P < 0.05)." (PMID 31315643, 2019). "Cancers express tryptophan catabolising enzymes indoleamine 2,3-dioxygenase 1 (IDO1) and tryptophan 2,3-dioxygenase (TDO2) to produce immunosuppressive tryptophan metabolites that undermine patients’ immune systems, leading to poor disease outcomes." (PMID 31795096, 2019). "Being a regulatory interface between IFN-gamma and IL-6, IDO1 promotes a pro-inflammatory response that plays a role in cancer neovascularization, by enhancing new blood vessel development." (PMID 30806743, 2019). "After 2000, immunosuppressive effect of IDO1 was revealed, its inhibitors set off a new upsurge in anti-cancer drugs." (PMID 32047753, 2019). "An interesting link between IFNγ and CSCs metabolism came from the observation that IFNγ triggers cancer dormancy through indolamine 2,3 dioxygenase (IDO1), an enzyme that catalyzes tryptophan metabolism." (PMID 31355143, 2019). "IDO1 is also constitutively expressed via an autocrine AhR-IL-6-STAT3 signaling loop in IDO1-positive cancer cells." (PMID 30777103, 2019). "Collectively, our data showed that H2S is a promising immunomodulator due to its negative regulation on the immunosuppressive enzyme IDO1 and represents a novel therapeutic target in cancer therapy." (PMID 30777103, 2019). "These research findings highlight the efficiency of IDO1 in cancer immunotherapy and other treatments." (PMID 31804586, 2019). "Cancer cells harness immune checkpoints such as cytotoxic T-lymphocyte-associated protein 4 (CTLA-4), programmed cell death protein 1 (PD-1) and indoleamine 2,3-dioxygenase 1 (IDO1) to evade immune control." (PMID 31112568, 2019). "IDO1 contributes to immune-regulation by converting L-Trp to Kyn and inducing amino acid starvation in cancer environment." (PMID 31423846, 2019). "When these two types of inhibitors are combined for either preclinical or clinical study, the high co-expression of both BET and IDO1 proteins in cancer cells is required." (PMID 31324754, 2019). "As a rate-limiting enzyme in the metabolism of essential amino acid tryptophan in the peripheral tissue, indoleamine 2,3-dioxygenase 1 (IDO1) is another promising target for cancer therapy." (PMID 30717285, 2019). "We highlight recent preclinical and clinical progress in targeting the IDO1 pathway in cancer therapeutics, including peptide vaccines, expression inhibitors, enzymatic inhibitors, and effector inhibitors." (PMID 30068361, 2018). "Three enzymes, namely IDO1, indoleamine 2,3-dioxygenase 2 (IDO2), and tryptophan 2,3-dioxygenase (TDO) are found controlling this step, but only IDO1 is proved to be sensitive in many cancer types." (PMID 29651242, 2018). "In the last decades, a growing number of studies showed the importance of IDO-1 in various pathologies, including, autoimmune diseases, allergy, and cancer." (PMID 30619249, 2018). "IDO1 is overexpressed in human cancer cells and suppresses effector T cell function and promotes regulatory T cells (Tregs)." (PMID 30338242, 2018). "Beyond the application of biomarkers and chemical inhibitors, IDO1 can be genetically targeted by genome editing tools that offer new therapeutic opportunities for cancer patients." (PMID 29445380, 2018). "Preclinical and clinical studies suggest that combinatorial immune checkpoint blockade and IDO1 inhibition provide durable therapeutic efficacy against cancer." (PMID 29685162, 2018). "It has also been established that the miRNA-regulated mechanisms that control the expression of PD-L1 are also involved in the repression of IDO1 in cancer cells." (PMID 29666625, 2018). "Nevertheless, other studies question the role of IDO1 overexpression in the adverse clinical outcome of certain cancers." (PMID 30150994, 2018).
cancer (continued). "Recent clinical trials suggest that the IDO1 inhibitors indoximod and epacadostat are well tolerated by cancer patients and exert anti-cancer effects in a subset of patients." (PMID 29685162, 2018). "Endogenous IDO1 expression is induced in a cancer cell line with interferon gamma and its activity is assessed by measuring kynurenine secreted into the media." (PMID 30112109, 2018). "First, by targeting a downstream effector molecule, indoximod differs from IDO1 enzyme inhibitors in being agnostic to the IDO/TDO enzyme(s) contributing to cancer pathogenesis." (PMID 30254983, 2018). "IDO1 expressed by cancer cells or infiltrating immune cells by depleting tryptophan in the local microenvironment activates GCN2K in the T-cells that infiltrate the lesion inhibiting their proliferation and inducing apoptosis." (PMID 30150994, 2018). "IDO1 is reported to be highly expressed in a wide range of cancers and IDO1 expression correlates with worse prognosis and reduced T cell infiltration." (PMID 29685162, 2018). "The effect of cancer cell IDO1 induction and inhibition on T cell activation is evaluated in a co-culture assay using Jurkat T cell line." (PMID 30112109, 2018). "Initial clinical studies employing a peptide-based vaccine approach to harness this anti-IDO1 response for the benefit of cancer patients have thus far been encouraging." (PMID 30400835, 2018). "IDO-1 is known for orchestrating mother's immune acceptance of the fetus, however some bacteria and cancers were found to exploit this pathway." (PMID 30564191, 2018). "A chief focus in the field is IDO1, a pro-inflammatory modifier that is widely overexpressed in cancers where it blunts immunosurveillance and enables neovascularization and metastasis." (PMID 30254983, 2018). "Constitutive IDO1 expression in human cancers is driven by cyclooxygenase 2 (COX-2) and PGE2 via the PKC and PI3K pathways." (PMID 30068361, 2018). "Indoleamine 2,3-dioxygenase 1 (IDO1) is an enzyme with immunomodulatory properties that has emerged as a potential immunotherapeutic target in human cancer." (PMID 29805749, 2018). "Several IDO1 inhibitors are being evaluated in clinical trials for various cancer indications as monotherapy and in combination with immune therapies (e.g. checkpoint inhibitors) or chemotherapy." (PMID 30112109, 2018). "Indoleamine-2,3-dioxygenase 1 (IDO1) catalyzes the oxidation of tryptophan into kynurenine and is partially responsible for acquired immune tolerance associated with cancer." (PMID 29921320, 2018). "Previous evidences indicated that D-1MT was more effective than DL-1MT as an anti-cancer agent and reversed the T cell suppression effect mediated by IDO1-expressing DCs." (PMID 30186285, 2018). "The mechanism of “cancer immunoediting” is the direct consequence of a T cell-dependent immunoselection process that drives the formation of IDO1+ tumors." (PMID 29445380, 2018). "Taken together, the data from the bioinformatics and the experimental studies reported here, suggest that high IMPACT expression benefits cancer cell survival during periods of accelerated tryptophan catabolism induced by IDO1." (PMID 30466445, 2018). "Indoleamine 2,3-dioxygenase 1 is also expressed in many types of cancer, and the majority of studies suggest that this enzyme plays a significant role in the escape of tumors from immunosurveillance." (PMID 30150994, 2018). "Targeting IDO1 represents a therapeutic opportunity in cancer immunotherapy beyond checkpoint blockade or adoptive transfer of chimeric antigen receptor T cells." (PMID 30068361, 2018). "In conclusion, there are many aspects to be revealed about the role of IDO1 in the escape of cancer from immunosurveillance." (PMID 30150994, 2018). "Further studies, e.g., on cancer in humans, are investigating the inhibition of IDO1 activity using applications of 1-methyltryptophan (1-MT) as a possible therapeutic approach." (PMID 30279361, 2018).
cancer (continued). "On the other hand, the anti-cancer effects of DL-1MT has been attributed to capacity to abrogate the anti-proliferative effects of IDO1-expressing mesenchymal stromal cells." (PMID 30186285, 2018). "Here, we utilize gene expression analysis of the cancer genome atlas (TCGA) and immunohistochemistry (IHC) to better understand the role and prognostic significance of IDO1 in EC." (PMID 29805749, 2018). "Regardless, selective inhibition of IDO1 is proposed to upregulate cellular immunity, with therapeutic potential in cancer, including CRC, and the influence of IDO1 on the gut microbiota is a factor that must be taken into account." (PMID 29468141, 2018). "Accordingly, inhibitors of the enzymatic activity and effector functions of IDO1 have been developed as tools to leverage cancer therapy." (PMID 30254983, 2018). "Paradoxically, the adaptive and innate immune systems that primarily protect against cancer development drive the formation of the highly aggressive and difficult-to-treat IDO1+ tumors." (PMID 29445380, 2018). "Important posttranslational control mechanisms affect the activity and half-life of IDO1 (e.g., NO, hypoxia, proteasomal degradation, phosphorylation) that should be considered in terms of cancer therapy." (PMID 29445380, 2018). "IDO1-reactive T cells are found not only in cancer patients, where pathophysiological elevation of IDO1 has been frequently noted, but even in healthy individuals." (PMID 30400835, 2018). "Based on the important role of IDO1 in cancer immune tolerance and development, targeting IDO1 is becoming an attractive approach in cancer therapeutic development." (PMID 30068361, 2018). "The results demonstrate that the unprecedented combination of melatonin and IDO1 inhibitors (particularly DL-1MT) improves the performance of the anti-cancer vaccine, leading to enhanced antitumor protection and activation of E7-specific CD8+ T cell response." (PMID 30186285, 2018). "In this work, we present that IDO1 inhibition by an miRNA miR-153 in combination with CAR T cells effectively enhances the efficacy of cancer cell killing that is mediated by CAR T cells." (PMID 29685162, 2018). "Indoleamine 2,3-dioxygenase 1 (IDO1) is an immunosuppressive enzyme that is highly overexpressed in various cancer cells and antigen-presenting cells." (PMID 29120388, 2017). "It appears that IDO1 pathway plays an essential function in cancer invasion and metastasis by promoting angiogenesis and inflammatory response." (PMID 28903363, 2017). "Human indoleamine 2,3-dioxygenase 1 (hIDO1) is an attractive cancer immunotherapeutic target owing to its role in promoting tumoral immune escape." (PMID 29167421, 2017). "Early clinical safety and efficacy data for the IDO1 inhibitor (epacadostat) in combination with anti-PD-1 (pembrolizumab) were promising for the treatment of various advanced cancers in a phase I/II study (e.g., melanoma, RCC, and NSCLC)." (PMID 27847783, 2016). "The combined decrease in Treg proliferation and increase in CTL activity seen with IDO1 inhibition supplies the rationale for clinical studies employing the combination of epacadostat and cancer vaccines or other immunotherapeutics." (PMID 27192116, 2016). "In most forms of human cancers, including BrCa, high IDO1 expression is positively correlated to poor prognosis." (PMID 26646699, 2016). "The finding of cytotoxic T cells specific for IDO1 in both healthy individuals and cancer patients provides further evidence for the immunogenicity of IDO1." (PMID 27192116, 2016). "Varying degrees of tumoral IDO1 expression has been described in biopsy material in a variety of human cancers." (PMID 26895379, 2016). "To investigate the expression pattern of IDO1 in various types of human cancers, we performed immunohistochemistry staining for IDO1 in samples of hepatocelluar carcinomas (n = 64)." (PMID 26895379, 2016).